PDCD4 (programmed cell death 4)
Diseases named in the same sentence as PDCD4 in open-access papers (continued):
Sharing a sentence is not in itself a finding about the gene and the disease.
esophageal squamous cell carcinoma (17 papers, 2010 to 2025). Esophageal squamous cell carcinoma (ESCC) is a type of esophageal carcinoma (EC) that can affect any part of the esophagus, but is usually located in the upper or middle third. "Up-regulation of this miRNA has resulted in down-regulation of PDCD4 expression, thus promoting proliferation and invasion of esophageal squamous cell carcinoma cells." (PMID 35402235, 2022). "CASC9 also recruiting EZH2 to PDCD4 promoter and alters H3K27me3 level and subsequently promotes esophageal squamous cell carcinoma metastasis by activating PDCD4 expression." (PMID 32677984, 2020). "The lncRNA taurine upregulated gene 1 (TUG1) (NCBI GeneID: 55000) was also demonstrated to suppress PDCD4 by recruiting EZH2 in esophageal squamous cell carcinoma (ESCC) through epigenetic modification." (PMID 31620370, 2019). "Treatment with isoalantolactone remarkably increased the expression of PDCD4 via the downregulation of miR-21, which exerts anticancer effects against esophageal squamous cell carcinoma." (PMID 31620370, 2019). "Similarly, downregulation of miR-21 consequently inhibits the proliferation, invasion, and migration of esophageal squamous cell carcinoma (ESCC) cells by negatively regulating the expression of PDCD4 or PTEN via the PTEN/PI3K/AKT signaling pathway." (PMID 34066762, 2021). "Furthermore, miR-183 enables to promote proliferation and invasion in esophageal squamous cell carcinoma (ESCC) by targeting PDCD4." (PMID 31210063, 2019). "For instance, CASC9 promoted esophageal squamous cell carcinoma (ESCC) progression by negatively regulating PDCD4 expression through recruiting EZH2." (PMID 36494339, 2022). "Promotes EMT and enhances invasiveness in esophageal squamous cell carcinoma by targeting PTEN and PDCD4." (PMID 40895189, 2025). "In esophageal squamous cell carcinoma, it was shown that TUG1 (long non-coding RNA Taurine Upregulated Gene 1) mediated cisplatin resistance by epigenetically suppressing PDCD4 (Programmed Cell Death 4) expression through recruiting EZH2." (PMID 36230683, 2022). "In esophageal squamous cell carcinoma (ESCC), miR-21, miR-130b, and miR-301 downregulate their target mRNAs, which include BMP6, PDCD4, and TIMP4, and induces EMT." (PMID 32967226, 2020). "In esophageal squamous cell carcinoma, CASC9 downregulates programmed cell death 4 protein." (PMID 35427373, 2022).
cervical carcinoma (15 papers, 2011 to 2024). A carcinoma arising from either the exocervical squamous epithelium or the endocervical glandular epithelium. "As an onco-miRNA, miR-21 is overexpressed in cervical cancer and implicated in the expression of the tumor suppressor gene programmed cell death 4 (PDCD4) and the chemokine CCL20 involved in tumor differentiation and metastasis." (PMID 39227808, 2024). "Similarly, GAS5 deficiency by siGAS5 also reduced miR-21 target protein PDCD4 expression in cervical cancer cells." (PMID 31620370, 2019). "One recent study has also reported reduced PDCD4 expression in cervical cancer cell lines which is in agreement with our findings in the clinical samples examined in this study." (PMID 22194833, 2011). "Our data reported herein in cervical cancer cell lines, and the evidence reported by other groups in tumor tissues, suggest that the regulatory genetic networks such as miR-21/PDCD4/AP-1 and miR-21/Let-7a/STAT3/PTEN, are highly complex and create a balance mechanism." (PMID 31427899, 2019). "An miR-21–regulated locus at the 3'UTR of PDCD4 has been reported in HeLa cervical carcinoma cells." (PMID 26252635, 2015). "Likewise, an inverse expression between miR-21 and programmed cell death protein 4 (PDCD4) in invasive cervical cancer was shown." (PMID 25192291, 2014). "Mounting evidence supports the significance of miR expression in cervical cancer, e.g., miR-21, which is reportedly overexpressed in various malignancies, promotes cell proliferation in HeLa cervical carcinoma cells by targeting programmed cell death 4 (PDCD4) expression." (PMID 33802524, 2021). "For instance, the lncRNA growth arrest-specific 5 (GAS5) can promote the expression of programmed cell death 4 (PDCD4) by sponging miR-21 and thereby enhance the CDDP sensitivity of cervical cancer cells." (PMID 34893064, 2021). "Previous studies revealed that PDCD4, PTEN and TPM1 are all transcripts targeted by mir-21 in various tissues and that PTEN is progressively underexpressed from normal tissue through to cervical cancer." (PMID 22194833, 2011).
osteosarcoma (14 papers, 2016 to 2023). A usually aggressive malignant bone-forming mesenchymal neoplasm, predominantly affecting adolescents and young adults. "NBAT1 (NCBI GeneID: 729177) functions as a ceRNA against miR-21 to increase the expression of the miR-21 target gene PDCD4 and then suppresses osteosarcoma growth and metastasis in vitro and in vivo." (PMID 31620370, 2019). "Overexpression of miR-202 promoted drug resistance by targeting programmed cell death 4 (PDCD4) in osteosarcoma." (PMID 28978183, 2017). "More importantly, it is reported that transfection of miR-202 mimics into osteosarcoma cells significantly promotes chemoresistance by targeting PDCD4 while transfection of miR-202 inhibitor enhances the chemosensitivity." (PMID 28341864, 2017). "Similarly, miR-183-5p targets Programmed cell death protein-4 (PDCD4) through the ERK1/2 pathway for promoting the invasion of osteosarcoma." (PMID 35453517, 2022). "Similarly, the lncRNA XIST inhibits cell growth and mobility by competitively binding to miR-21-5p for PDCD4 up-regulation in osteosarcoma." (PMID 31620370, 2019). "The transfection of miR-433 mimics into osteosarcoma cell lines could decrease apoptosis by PDCD4." (PMID 31620370, 2019). "Exosomal miR-208a derived from the BMSC has been shown to negatively target programmed cell death protein 4 (PDCD4) in order to activate the ERK1/2 signaling pathway, thus promoting the proliferation, migration, and invasion of osteosarcoma cells." (PMID 36678850, 2023). "XIST is another potential biomarker of osteosarcoma which has been reported to modulate osteosarcoma proliferation and invasion through miR-320b/RAP2B, miR-193a-3p/RSF1, miR-21-5p/PDCD4, and miR-195-5p/YAP axis." (PMID 33639865, 2021). "Furthermore, exosomal miR-208a inhibited programmed cell death protein 4 (PDCD4) and then activated ERK1/2 signaling pathway to enhance the aggressiveness of osteosarcoma." (PMID 35592419, 2022). "In osteosarcoma, ectopic expression of hsa-miR-433 decreased apoptosis in tumor cells by targeting programmed cell death 4 (PDCD4), indicating that hsa-miR-433 may be a potential molecular target for osteosarcoma treatment." (PMID 34064637, 2021). "Interestingly, up-regulation of these genes by both CSL and PDCD4 gene silencing was observed in HDFs and osteosarcoma (fibroblast-like) cell line Saos-2 cells, but not human primary keratinocytes (HKCs) or HeLa cells." (PMID 27542230, 2016).
lymphoma (11 papers, 2006 to 2025). A malignant (clonal) proliferation of B- lymphocytes or T- lymphocytes which involves the lymph nodes, bone marrow and/or extranodal sites. "Although PDCD4 deficient mice have activated lymphocytes that produce cytokines that promote oncogenesis and develop spontaneous lymphomas which frequently metastasise, these mice were found to be resistant to inflammatory disease such as autoimmune encephalomyelitis and diabetes." (PMID 35847932, 2022). "Absence or very low frequency mutations detected by NGS in LKB1, P70S6K and PDCD4 genes in CTCL/SS lymphomas furthermore support this hypothesis." (PMID 30518812, 2019). "PDCD4 functions as a tumor suppressor, and PDCD4 knockdown mice develop spontaneous lymphomas and show a significantly reduced life span compared with wild-type siblings." (PMID 41439995, 2025). "We previously demonstrated that activation of BCR signaling in primary CLL cells downregulated expression of PDCD4, an inhibitor of the translational initiation factor eIF4A and a potential tumor suppressor in lymphoma." (PMID 35306137, 2022). "Here we show that MYC expression is also associated with PDCD4 down-regulation in CLL cells in vivo and characterize the signaling pathways that mediate BCR-induced PDCD4 down-regulation in CLL and lymphoma cells." (PMID 35306137, 2022). "Over-expression of PDCD4 inhibits tumor growth and metastasis, whereas PDCD4 knockout mice develop spontaneous tumors (lymphomas)." (PMID 27542230, 2016). "PDCD4-knockout mice developed spontaneous lymphomas with systematic dissemination and frequent liver/renal metastasis." (PMID 27852288, 2016). "In lymphoma cells, PDCD4 degradation was predominantly dependent on signaling via the AKT pathway." (PMID 35306137, 2022). "Although SNK/T cells share common biological properties, statistical analysis using a GeneSifter® revealed that a subset of genes including PDCD4 may contribute to the development of lymphoma." (PMID 16449999, 2006).
bladder cancer (10 papers, 2009 to 2024). "MiR-150-5p functions as a tumor promoter in reducing chemosensitivity and promoting invasiveness of muscle-invasive bladder cancer cells lines by targeting PDCD4, while miR-222-3p overexpression in bladder cancer tissues is associated with poor prognosis possibly via suppression of p27Kip1." (PMID 29599914, 2018). "It appears that in CP-resistant bladder cancer cells, increasing the expression of PDCD4 is important." (PMID 32503307, 2020). "The upregulation of PDCD4 is associated with the inhibition of the JNK/c-Jun signaling pathway to suppress EMT and sensitize bladder cancer cells to CP chemotherapy." (PMID 32503307, 2020). "In bladder cancer cells, PDCD4 overexpression enhances sensitivity to cisplatin via regulation of the JNK/c-JUN pathway." (PMID 32260415, 2020). "In bladder cancer, PDCD4 modulate DDP sensitivity via regulating JNK/c-Jun signaling pathway." (PMID 38993556, 2024). "Moreover, further recent studies confirmed the regulation of PDCD4 by miR-21 in colon, breast, and bladder carcinoma." (PMID 31620370, 2019). "For example, miR-21, as a classic oncogene, was identified as the key regulator of PDCD4 by targeting its 3′-untranslated region (UTR) to promote tumor proliferation, migration, and invasion in colon, breast, and bladder carcinoma." (PMID 31620370, 2019).
multiple myeloma (10 papers, 2014 to 2025). "Berberine, a natural alkaloid, inhibits the proliferation of multiple myeloma cells by downregulating miR-21-5p and upregulating its target, programmed cell death 4 (PDCD4)." (PMID 36612314, 2023). "Exosomal miR-21 from NSCLC cells facilitates osteoclastogenesis by targeting PDCD4 and inhibition of miR-21 impairs osteoclast activity in multiple myeloma by targeting OPG and PIAS3." (PMID 33800656, 2021). "In the process of CAM-DR, the adhesion of myeloma cells to fibronectin (FN) via its surface integrinβ1 induces the expression of miR-182, which suppresses the expression of human programmed cell death 4 (PDCD4) and triggers downstream drug-resistance mechanisms." (PMID 37048103, 2023). "Short interfering RNA depletion of PDCD4 could preserve BBR-induced cytotoxicity in multiple myeloma cells." (PMID 34885950, 2021). "Depletion of PDCD4 by short interfering RNA could rescue berberine-induced cytotoxicity in multiple myeloma cells." (PMID 25000828, 2014). "BBR has previously demonstrated modulations to miR-21 of U266 and RPMI-8266 cells, another IgG-producing myeloma cell line, potentially through IL-6/STAT3, and the consequential increase in programmed cell death 4 gene expression." (PMID 41294852, 2025). "However, in both CLL and B-lymphoma cells, anti-IgM-induced PDCD4 down-regulation was due to increased proteasomal degradation as it was reversed by PSI, including bortezomib which is used to treat multiple myeloma and mantle cell lymphoma." (PMID 35306137, 2022).
ischemia (9 papers, 2015 to 2024). A hypoperfusion of the BLOOD through an organ or tissue caused by a PATHOLOGIC CONSTRICTION or obstruction of its BLOOD VESSELS, or an absence of BLOOD CIRCULATION. "PDCD4-mediated Akt signaling pathway results in vascular endothelial cell injury caused by lower-extremity ischemia-reperfusion in rats." (PMID 35983977, 2022). "In the current study, we first determined the functional interaction among MEG3, microRNA-21 (miR-21), and programmed cell death 4 (PDCD4) in ischemia." (PMID 29238035, 2017). "Negative correlation between miR-21 and proinflammatory programmed cell death 4 (PDCD4) has also been reported in TEC with induction of ischemia." (PMID 25750628, 2015). "In vitro gain-of-function and loss-of-function studies of miR-21 confirm that it protects against ischemia-induced cardiomyocytes apoptosis by inhibiting programmed cell death protein 4 (PDCD4) and activator protein 1 (AP-1)." (PMID 26462179, 2015). "In addition, MSCs from gingival tissues can reduce apoptosis through the MEG3/miR-21a-5p/PDCD4 axis, thus protecting the nerve from ischemia–reperfusion injury in the retina." (PMID 38627703, 2024). "A few in vitro studies have hypothesized this cardioprotective role during ischemia to be mediated by upregulating HIF-1α through the regulation of the PTEN/Akt pathway as well as inhibiting its proapoptotic target gene PDCD4." (PMID 33114482, 2020). "Although here we described that MEG3 competed with PDCD4 mRNA for binding to miR-21 in ischemia, we didn’t exclude the possibility of other targets of MEG3 or miR-21 which may also contribute to the ischemic neuronal death." (PMID 29238035, 2017). "In the mouse model of ischemia/reperfusion lung injury, the anti-apoptotic miR-21-5p in MSC-derived EVs was transported to alveolar macrophages, contributing to macrophage reprogramming toward M2 macrophages via phosphatase and tensin homolog (PTEN) and programmed cell death protein 4 (PDCD4)." (PMID 38247814, 2024).
polycystic ovary syndrome (9 papers, 2018 to 2026). A disorder that manifests as multiple cysts on the ovaries. "In polycystic ovary syndrome patients, a higher PDCD4 expression is associated with insulin resistance, lipid metabolism disorders, and granular cell apoptosis." (PMID 41439995, 2025). "For instance, miR-16 promoted ovarian granulosa cell (GC) proliferation and inhibited apoptosis through directly targeting programmed cell death protein 4 (PDCD4) in polycystic ovarian syndrome (PCOS)." (PMID 30227605, 2018). "Some studies demonstrated that mesenchymal stem cells derived extracellular vesicles could promote proliferation and inhibits apoptosis of cumulus cells in polycystic ovary syndrome (PCOS) via transferring encapsulated miR-323-3p and targeting PDCD4." (PMID 34745016, 2021).
renal cell carcinoma (9 papers, 2014 to 2025). "For instance, in renal cell carcinoma, fluvastatin inhibits the kinase p70S6Kα, accompanied by an increase in the expression of PDCD4 and the formation of the eIF4E-binding protein-eIF4E complex, inducing apoptosis." (PMID 38672098, 2024). "In renal cell carcinoma, miR-21 expression has been shown to promote cell invasiveness and angiogenesis by directly targeting the programmed cell death gene 4 (PDCD4)/c-Jun signaling pathway." (PMID 32492882, 2020). "PDCD4 is down-regulated in several types of human cancer, and is an independent predictor of poor prognosis in renal cell carcinoma patients." (PMID 25000828, 2014). "However, miRNAs in general have been studied in oncology because they are often overexpressed in some cancers, as in the case of miRNA-21, and its predominant role in promoting cell invasiveness in renal cell carcinoma through the PDCD4/c-jun pathway (AP-1)." (PMID 36555142, 2022). "In previous works, PDCD4 was reported to be reduced in human renal cell carcinoma patients." (PMID 33969128, 2021). "Consistent with previous findings, miRNA-21 is overexpressed in renal cell carcinoma (RCC) tissues and regulates the growth, apoptosis, and cell cycle progression of RCC cells, as well as the expression of programmed cell death 4 (PDCD4) and TPM1." (PMID 37686101, 2023). "IPA confirmed that the target molecules identified in our study (ERK, FOXO1, FOXO3, JNK1, PDCD4, AKT3) form an interactive network with shikonin, which further leads to renal cancer, renal cell carcinoma, and apoptosis." (PMID 41462911, 2025).
colon adenocarcinoma (8 papers, 2014 to 2022). "A similar switch in localization was associated with tumor progression in colon adenocarcinoma, thus suggesting cytoplasmic PDCD4 is a hallmark of progressive cancer across multiple malignancies." (PMID 33801444, 2021). "The overexpressed of miRNA-181b mimic in SW480 colon adenocarcinoma cells resulted in an increase in proliferation and migration, whereas apoptosis and PDCD4 protein expression decreased, with only a marginal decrease in mRNA." (PMID 35847932, 2022). "Originally, transfection of an miRNA-21 mimic and a luciferase-PDCD4 reporter construct into Colo206f colon adenocarcinoma cells showed decreased fluorescence and direct binding of miRNA-21 to the 3’-UTR of PDCD4." (PMID 35847932, 2022). "In addition, the oncogenic role of this exosomal miRNA has also been found to promote chemoresistance via targeting the tumor suppressor PDCD4 in colon adenocarcinoma cells." (PMID 34572835, 2021). "We also found that PDCD4 negatively regulated the cyclin-dependent kinase inhibitor p21Waf1/Cip1 in HUVECs, which agrees with the finding that siRNA knockdown of PDCD4 expression led to increased expression of p21Waf1/Cip1 in HCT116 colon adenocarcinoma cells and human KT1 cells." (PMID 24626527, 2014). "We chose the human colonic adenocarcinoma cell line HCA-7 isolated from a Dukes' B tumour because it has high endogenous levels of COX-2 and following treatment with the COX-2 inhibitor NS398 increases expression of PDCD4." (PMID 25310697, 2014). "In addition, pharmacological downregulation of cyclooxygenase-2 (cox-2) activity in HCA-7 human colonic adenocarcinoma cell line resulted in an increase in PDCD4 protein-, but not mRNA expression, again implying that PDCD4 is controlled by inflammation." (PMID 35847932, 2022).